ALS2 (alsin Rho guanine nucleotide exchange factor ALS2)
Description:
May act as a GTPase regulator. Controls survival and growth of spinal motoneurons (By similarity).
Synonyms: ALS2CR6; ALSJ; IAHSP; PLSJ
Tractability: PROTAC: ubiquitination databases record sites on it; its protein half-life has been measured.
Gene: Protein-coding gene on chromosome 2 (201,700,267 to 201,782,112, reverse strand). Ensembl gene ENSG00000003393.
Subcellular location (Human Protein Atlas): Cytosol; Vesicles
Pathways (Reactome):
Signal Transduction: RAC1 GTPase cycle
Vesicle-mediated transport: RAB GEFs exchange GTP for GDP on RABs
Gene Ontology:
Molecular function: GTPase activator activity; guanyl-nucleotide exchange factor activity; identical protein binding; protein binding; protein homodimerization activity; protein serine/threonine kinase activator activity; small GTPase binding
Biological process: lysosomal transport; neuron projection morphogenesis; positive regulation of GTPase activity; positive regulation of protein kinase activity; protein homooligomerization; regulation of endosome size; endosomal transport; endosome organization; positive regulation of Rac protein signal transduction; regulation of postsynaptic membrane neurotransmitter receptor levels
Cellular component: centrosome; cytosol; dendrite; early endosome; nucleus; protein-containing complex; vesicle; cytoplasm; growth cone; lamellipodium; ruffle; dendritic spine; glutamatergic synapse; postsynaptic density
Genetic constraint (gnomAD): Loss-of-function variants: 114 observed, 205.3 expected, observed/expected ratio (o/e) 0.56, 90% interval 0.48 to 0.65. The upper end of that interval is the gene's LOEUF score, 0.65, which puts it in group 2 of 6, group 1 being the genes least tolerant of losing a copy. Missense variants: 1,675 observed, 2,043.2 expected, observed/expected ratio (o/e) 0.82, 90% interval 0.79 to 0.85. Synonymous variants: 698 observed, 748.68 expected, observed/expected ratio (o/e) 0.93, 90% interval 0.88 to 0.99.
Gene-disease validity (ClinGen):
ClinGen rates the evidence that ALS2 causes each of these diseases.
ALS2-related motor neuron disease (autosomal recessive): Definitive. Any motor neuron disease in which the cause of the disease is a mutation in the ALS2 gene.
Homologues: Orthologues: chimpanzee ALS2 (99% identical), macaque ALS2 (99% identical), dog ALS2 (95% identical), pig ALS2 (93% identical), rabbit ALS2 (92% identical), mouse Als2 (92% identical), rat Als2 (90% identical), guinea pig ALS2 (84% identical), tropical clawed frog als2 (68% identical), zebrafish als2b (61% identical), zebrafish als2a (52% identical), Drosophila melanogaster ca (11% identical), and 3 more. Paralogues in human: HERC1 (16% identical), RPGR (7% identical), RCC2 (7% identical), RCBTB1 (6% identical), RCCD1 (6% identical), RCBTB2 (6% identical), RCC1 (6% identical), RCC1L (6% identical), SERGEF (5% identical).
Diseases named in the same sentence as ALS2 in open-access papers:
ALS2 is named in the same sentence as 50 diseases in open-access papers, as found by Europe PMC text mining. Sharing a sentence is not in itself a finding about the gene and the disease. The quoted sentences say what the papers report.
amyotrophic lateral sclerosis (16 papers, 2008 to 2023). Amyotrophic lateral sclerosis (ALS) is a neurodegenerative disease characterized by progressive muscular paralysis reflecting degeneration of motor neurons in the primary motor cortex, corticospinal tracts, brainstem and spinal cord. "Infantile-onset Ascending Hereditary Spastic Paralysis, Juvenile Primary Lateral Sclerosis and Juvenile Amyotrophic Lateral Sclerosis are all motor neuron diseases related to mutations on the ALS2 gene, encoding for a 1657 amino acids protein named Alsin." (PMID 35053075, 2022). "Another example is provided by the ALS2 (amyotrophic lateral sclerosis 2-juvenile) locus, which encodes for a protein where mutations have been associated to an autosomal recessive form of juvenile-onset amyotrophic lateral sclerosis (jALS)." (PMID 20041218, 2009). "Interestingly, activation of Rab5 on mitochondria depends on the Rab5-GEF ALS2/Alsin, encoded by a gene mutated in amyotrophic lateral sclerosis (ALS)." (PMID 29469808, 2018). "Amyotrophic lateral sclerosis (ALS), one of the most common motor neuron diseases, is associated with the loss of function of the ALS2 gene." (PMID 38203282, 2023). "Pathogenic variants in ALS2 have been detected mostly in juvenile cases of amyotrophic lateral sclerosis (ALS), affecting mainly children and teenagers." (PMID 35208248, 2022). "Alsin is the gene product of ALS2, which is mutated in multiple neurodegenerative disorders such as juvenile amyotrophic lateral sclerosis (ALS), juvenile primary lateral sclerosis (JPLS), and infantile-onset ascending hereditary spastic paralysis (IAHSP)." (PMID 29469808, 2018). "The gene encoding Alsin, ALS2, is a causative gene of several motoneuron degenerative diseases, including juvenile amyotrophic lateral sclerosis (ALS), primary lateral sclerosis, and infantile-onset ascending hereditary spastic paralysis." (PMID 25879033, 2015). "Homozygous loss-of-function mutations in ALS2 are known to cause juvenile-onset amyotrophic lateral sclerosis (ALS), one of the many neurological conditions having overlapping symptoms with many neurological phenotypes." (PMID 25474699, 2014). "Among the more than sixty identified genes related to amyotrophic lateral sclerosis (ALS), there are eight encoded key cytoskeletal proteins, including ALS2 and PFN1." (PMID 37443816, 2023). "Among the novel regulatory targets of Nrf2 we identified is Als2, a protein involved in amyotrophic lateral sclerosis (Lou Gehrig's disease)." (PMID 18769717, 2008). "Mutations in the ALS2 gene have been shown to cause infantile-onset ascending hereditary spastic paraplegia (IAHSP), juvenile-onset primary lateral sclerosis (JPLS), and amyotrophic lateral sclerosis (ALS)." (PMID 30934641, 2019).
motor neuron diseases (12 papers, 2009 to 2022). "Mutations of the ALS2 gene, which encodes for the protein Alsin, are linked to three recessive motor neuron diseases characterized by early onset." (PMID 35053075, 2022). "As of now, 82 patients with early-onset motor neuron diseases due to variants in ALS2 have been identified." (PMID 35208248, 2022). "More than 100 pathogenic variants in ALS2 have been reported in patients with motor neuron diseases." (PMID 35208248, 2022). "Recessive mutations in ALS2 gene lead to a spectrum of motor neuron disorders with a predominantly upper motor neuron (UMN) degeneration signature." (PMID 35208248, 2022). "It has been reported that UXT can interact with Als2, a gene that causes mutations in autosomal recessive forms of motor neuron disease, and the interaction of Als2 and UXT has an important role in the activation of the NF-κB pathway." (PMID 32699605, 2020). "Several ALS2 missense or in-frame deletion mutations have been demonstrated to be associated with different but relatively similar motor neuron disorders, including ALS." (PMID 33276461, 2020). "Many studies reported that common motor neuron diseases have a close relationship with mutations in ALS2, resulting in juvenile lateral sclerosis and infantile-onset ascending spastic paralysis." (PMID 27917343, 2016). "Mutations in ALS2 were identified in juvenile cases of motor neuron diseases, including ALS." (PMID 29282133, 2017). "ALS2 is a causative gene for a juvenile autosomal recessive form of motor neuron diseases (MNDs), including amyotrophic lateral sclerosis 2 (ALS2) (OMIM 205100), juvenile primary lateral sclerosis (PLSJ) (OMIM 606353), and infantile-onset ascending hereditary spastic paralysis (IAHSP) (OMIM 607225)." (PMID 20339559, 2010). "ALS2 deficiency accounts for a number of juvenile recessive motor neuron diseases (MNDs)." (PMID 20339559, 2010). "Therefore, our findings reveal a negatively regulatory mechanism of alsin in Rab5-mediated endosomal trafficking, suggesting that enhanced endosomal degradation in ALS2-/- neurons may underlie the pathogenesis of motor neuron degeneration in ALS2 and related motor neuron diseases." (PMID 19630956, 2009). "Taken together, our data indicate that excessive endosomal degradation in ALS2-/- neurons may contribute to the pathogenesis of ALS2 and related motor neuron diseases." (PMID 19630956, 2009). "ALS2/alsin is a RAB5GEF and its depletion is responsible for different recessive forms of motor neuron diseases." (PMID 26861397, 2016).
hereditary spastic paraplegia (8 papers, 2009 to 2026). Hereditary spastic paraplegias (HSP) comprise a genetically and clinically heterogeneous group of neurodegenerative disorders characterized by progressive spasticity and hyperreflexia of the lower limbs. "ALS2 mutations are also known to cause complicated, infantile-onset forms of hereditary spastic paraplegia." (PMID 25474699, 2014). "Autosomal recessive mutations in the ALS2 gene lead to a clinical spectrum of motor dysfunction including juvenile onset amyotrophic lateral sclerosis (ALS2), primary lateral sclerosis and hereditary spastic paraplegia." (PMID 19630956, 2009). "Infantile-onset Ascending Hereditary Spastic Paralysis (IAHSP) is an ultrarare, autosomal recessive form of Hereditary Spastic Paraplegia (HSP), caused by mutations in the ALS2 gene, which encodes the protein ALSIN." (PMID 41657105, 2026). "Furthermore, hereditary spastic paraplegia (HSP) is another complex disease that exhibits some genetic overlap with ALS through mutations in ALS2 and SPG11." (PMID 29670510, 2018). "Mutations in ALS2 were described to be responsible for a recessive form of juvenile-onset ALS, although later studies have suggested that ALS2-induced disease phenotypes are more related to slowly progressive, juvenile forms of hereditary spastic paraplegia." (PMID 25249940, 2014).
infantile-onset ascending hereditary spastic paralysis (8 papers, 2010 to 2026). Infantile-onset ascending hereditary spastic paralysis (IAHSP) is a very rare motor neuron disease characterized by severe spasticity of the lower limbs in early life, progression of spasticity to the upper limbs in late childhood, and dysarthria. "Loss of function mutations in the ALS2 gene accounts for juvenile recessive amyotrophic lateral sclerosis (ALS2), juvenile primary lateral sclerosis (JPLS), and infantile-onset ascending hereditary spastic paralysis (IAHSP)." (PMID 22852081, 2012). "Recessive mutations in the ALS2 gene are responsible for distinct MND conditions, namely Infantile-onset ascending hereditary spastic paralysis (IAHSP, OMIM:607225), Juvenile Primary Lateral Sclerosis (JPLS, OMIM:606353), and Juvenile Amyotrophic Lateral Sclerosis (JALS OMIM:205100)." (PMID 35053075, 2022).
juvenile primary lateral sclerosis (8 papers, 2010 to 2024). Juvenile primary lateral sclerosis (JPLS) is a very rare motor neuron disease characterized by progressive upper motor neuron dysfunction leading to loss of the ability to walk with wheelchair dependence, and subsequently, loss of motor speech production. "Mutations in the ALS2 gene cause three distinct disorders: infantile ascending hereditary spastic paraplegia, juvenile primary lateral sclerosis, and autosomal recessive juvenile amyotrophic lateral sclerosis." (PMID 25302125, 2014). "Besides ALS2, juvenile primary lateral sclerosis (JPLS) has also been linked to ERLIN2 variants." (PMID 38276084, 2024). "Approximatively 100 pathogenic variants in ALS2 have been identified in patients with MNDs and cause a number of autosomal recessive juvenile-onset MNDs, including ALS type 2 (ALS2), infantile-onset ascending hereditary spastic paraplegia (IAHSP) and juvenile primary lateral sclerosis (JPLS)." (PMID 38002924, 2023).
Primary lateral sclerosis (7 papers, 2009 to 2022). "Deletion mutations in the short transcript cause ALS2 and those in the long transcript lead to juvenile primary lateral sclerosis (PLS)." (PMID 23941283, 2013). "The disease is characterized by autosomal-recessive hereditary transmission, caused by mutations in the ALS2 gene, unlike the adult primary lateral sclerosis, which is inherited in an autosomal-dominant manner." (PMID 35053075, 2022). "At least 12 different mutations in ALS2 have been reported in juvenile ALS and primary lateral sclerosis (PLS)." (PMID 30721407, 2019). "Literature search reveals that ALS2-related disorders include Autosomal Recessive Juvenile Amyotrophic Lateral Sclerosis, Infantile-Onset Ascending Hereditary Spastic Paralysis and Juvenile Primary Lateral Sclerosis, but not PK." (PMID 21731658, 2011).
juvenile amyotrophic lateral sclerosis (4 papers, 2018 to 2024). Juvenile amyotrophic lateral sclerosis (JALS) is a very rare severe motor neuron disease characterized by progressive upper and lower motor neuron degeneration causing facial spasticity, dysarthria, and gait disorders with onset before 25 years of age. "Multiple studies have reported dystonia in infantile-onset ascending HSP and juvenile amyotrophic lateral sclerosis associated with ALS2 variants." (PMID 37251230, 2023).
Dystonia (3 papers, 2014 to 2023). An abnormally increased muscular tone that causes fixed abnormal postures. "A recent study reported patients with ALS2 with nonsense and frameshift mutations in the Alsin gene who presented with generalized dystonia and cerebellar signs." (PMID 26213621, 2015). "Recently, Sheerin and colleagues reported nonsense and frameshift mutations in ALS2 in individuals presenting with generalized dystonia and cerebellar signs." (PMID 25474699, 2014).
motor neuron degeneration (3 papers, 2009 to 2021). "Several genes mutated in ALS patients and implicated in motor neuron degeneration have been studied in zebrafish, including superoxide dismutase (SOD1), alsin (ALS2), the elongated protein 3 (ELP3), FUS, and TDP-43." (PMID 33499374, 2021). "In addition, various syndromes of motor neuron degeneration are caused by mutations in other genes such as Progranulin/GRN, Angiogenin/ANG, CHMP2B, Spastin/SPAST, PRPH, VAPB, and Alsin/ALS2." (PMID 25955410, 2015).
liposarcoma (2 papers, 2011 to 2012). A usually painless malignant tumor that arises from adipose tissue. "These include the genes codingfor alsin (ALS2), vesicle associated membrane protein B (VAPB), senataxin (SETX), TAR-DNA-bindingprotein (TDP-43), fused in sarcoma or translocated in liposarcoma(FUS/TLS), and optineurin (OPTN)." (PMID 21541368, 2011).
oral candidiasis (2 papers, 2022 to 2025). Infection of the mucosal lining of the mouth with the fungus Candida albicans. "Als2 was visible on C. albicans yeast cells recovered from a murine model of oral candidiasis, demonstrating Als2 production both in vivo and in vitro." (PMID 35802580, 2022). "MAb 2-C6 immunolabeled C. albicans yeast cells recovered from a murine model of oral candidiasis documenting ALS2 transcription in vivo." (PMID 35802580, 2022). "Rare Als2-positive yeast cells were recovered from a murine model of oral candidiasis." (PMID 35802580, 2022). "Furthermore, high percentages of expression for ALS1, ALS2, ALS3, ALS4, ALS5, and ALS9 strains of C. albicans from oral candidiasis during the infection of a reconstituted human oral epithelium have been reported." (PMID 40943639, 2025).
Spastic paraplegia (2 papers, 2021 to 2023). Complete loss of the ability to move the lower limbs accompanied by spasticity of the lower limbs. "The finding of ALS2 mutations in our F1 and F2 families allowed a precise diagnosis of the patients despite of the scarce clinical data suggesting cases of spastic paraplegia." (PMID 33409823, 2021). "Among the patients with ALS2, SACS, and L1CAM variants in our cohort, several exhibited clinical symptoms characteristic of spastic paraplegia." (PMID 37251230, 2023).
Bovine mastitis (1 paper, 2023). INFLAMMATION of the UDDER in cows. "We demonstrated applicability of the cell-free expression system for rapid screening and comparison of antibacterial activity of chimeric lysin candidates and verified the antibacterial activity of ALS2 against the major S. aureus genotype causing bovine mastitis in Korea." (PMID 37107029, 2023). "Thus, the simple and rapid screening method can be applied to select functional chimeric lysins and define mutations affecting antibacterial activity, and ALS2 may be useful in itself and as a lead molecule to control bovine mastitis." (PMID 37107029, 2023).
candidiasis (1 paper, 2020). Infection with the organism Candida. "In C. albicans, agglutinin-like sequence (ALS) genes, including ALS1 and ALS2, play a crucial role in adhesion-mediated biofilm formation by C. albicans to cause candidiasis." (PMID 33193145, 2020).
Childhood onset (1 paper, 2014). Onset of disease at the age of between 1 and 5 years. "Through linkage analysis, homozygosity mapping and whole-exome sequencing, we identified a novel splice-site mutation in ALS2 as a cause of a childhood-onset neurological disease with complex clinical presentation, thereby establishing a genetic diagnosis of juvenile-onset ALS in this family." (PMID 25474699, 2014).
clear cell renal cell carcinoma (1 paper, 2020). "To evaluate the relevance of this association in cancer, we assessed the expression of ALS2 in clear cell renal cell carcinoma (CCRCC) biopsies, since this type of cancer is associated with mutations in VHL6." (PMID 33339852, 2020).
distal myopathy (1 paper, 2021). Distal myopathy refers to a group of muscle diseases which share the clinical pattern of predominant weakness and atrophy beginning in the feet and/or hands. "Other allelic neurological disorders with the same gene associations are ataxia with oculomotor apraxia (SETX), HSP (ALS2, SPG11, ERLIN1, and DDHD1), JPLS (ALS2), dHMN (SIGMAR1), distal myopathy (GNE), and distal SMA (BICD2)." (PMID 34946884, 2021).
lateral sclerosis (1 paper, 2012). Primary lateral sclerosis (PLS) is an idiopathic non-familial motor neuron disease characterized by slowly progressive upper motor neuron dysfunction leading to spasticity, mild weakness in voluntary muscle movement, hyperreflexia, and loss of motor speech production. "Expression of SLC24A5, MMP115, and TYR, and genes for crystalline alphaB (CRYAB), Shikimate 5-dehydrogenase and amyotrophic lateral sclerosis 2 (ALS2) were commonly depressed in AV and CV samples relative to BL controls." (PMID 22500953, 2012).
lung carcinoma (1 paper, 2020). "Indeed, we showed here that ALS2 is required for (hypoxic) stimuli-induced migration of tumor cells, as observed in renal cell carcinoma, murine melanoma and lung carcinoma cell lines." (PMID 33339852, 2020).
melanoma (1 paper, 2020). A malignant, usually aggressive tumor composed of atypical, neoplastic melanocytes. "However, our data obtained in B16-F10 melanoma cells indicate that neither ALS2 knockdown nor 24 h hypoxia affected cell viability." (PMID 33339852, 2020).
mental disorder (1 paper, 2016). A disease that has its basis in the disruption of mental process.
renal cell carcinoma (1 paper, 2020). "Finally, immunohistochemical analyses in patient biopsies with renal cell carcinoma showed that elevated HIF-1α correlates with increased ALS2 expression." (PMID 33339852, 2020). "Moreover, ALS2 and Rab5 activity were elevated both in a model of endogenous HIF-1α stabilization (renal cell carcinoma) and by following expression of stable non-hydroxylatable HIF-1α." (PMID 33339852, 2020).
vaginal candidiasis (1 paper, 2025). "High prevalence of expression of ALS1, ALS2, ALS3, and ALS9 has also been described in strains from vaginal candidiasis using an infection model in a reconstituted human vaginal epithelium (RHVE)." (PMID 40943639, 2025).